SRPK2 (SRSF protein kinase 2)
Diseases named in the same sentence as SRPK2 in open-access papers (continued):
Sharing a sentence is not in itself a finding about the gene and the disease.
HIV-1 infection (1 paper, 2011). The type species of lentivirus and the etiologic agent of acquired immunodeficiency syndrome (AIDS). "Support for this hypothesis can be found in the observation that HIV-1 infection is associated with changes in SR protein phosphorylation/abundance that could be reversed upon overexpression of SR protein kinase 2 (SRPK2)." (PMID 21682887, 2011).
liver disease (1 paper, 2025). "A recent paper found the regulation of alternative splicing by SRPK2 is implicated in lipogenesis in humans with alcohol-associated liver disease, thus making it a potential drug target." (PMID 39863868, 2025).
malaria (1 paper, 2016). Malaria is a serious and sometimes fatal disease caused by a parasite that commonly infects a certain type of mosquito which feeds on humans. "In addition to the genes in the cell-cell adhesion cadherin-catenin, and related pathways, two regulators of alternative splicing (RBFOX1 and SRPK2) in neurons and the vasculature showed very strong environmental correlations with malaria." (PMID 26744416, 2016).
metastatic melanoma (1 paper, 2022). A melanoma that has spread from its primary site to another anatomic site. "Taken together, these findings suggest different functional roles for SRPK1/2 in metastatic melanoma and highlight the relevance of pursuing selective pharmacological inhibitors of SRPK2." (PMID 36212152, 2022). "In summary, we have shown that in metastatic melanoma, high expression of SRPK1/2, especially SRPK2, contributes to the poor prognosis of patients." (PMID 36212152, 2022).
myeloproliferative disorder (1 paper, 2016). A clonal hematopoietic stem cell disorder, characterized by proliferation in the bone marrow of one or more of the myeloid (i.e., granulocytic, erythroid, megakaryocytic, and mast cell) lineages. "This analysis focused on genes (Srpk2, Hes1, Mtor, Pdp1, Meis1, Gfi1, Foxo3, Stra13, Hif1α, and Cebpε) involved in HSC proliferation; maintenance of quiescence, growth, and stem cell exhaustion; and development of myeloproliferative disorder in young and geriatric mice." (PMID 27366154, 2016).
osteosarcoma (1 paper, 2023). A usually aggressive malignant bone-forming mesenchymal neoplasm, predominantly affecting adolescents and young adults. "Further, the endogenous binding relationship between SRPK2 and BRD4 in osteosarcoma cells was verified and the main binding site was analyzed in the CTD domain of BRD4." (PMID 37993451, 2023). "Finally, 18 paired osteosarcoma tissues and normal osteogenic tissues were selected from the GEO database (cancerous tissue matched 1:1 with adjacent osteogenic tissue, GSE99671) to analyze the expression correlation between BRD4, SRPK2, SRSF2 and ACSL3." (PMID 37993451, 2023). "It shows that the expression of ACSL3 was not correlated with the expression of BRD4 and SRPK2, but positively correlated with SRSF2, which is consistent with our findings in 10 cancerous tissues surgically removed from patients with osteosarcoma." (PMID 37993451, 2023).
serous ovarian cancer (1 paper, 2021). "Since mutations in RNA modification genes have been reported to be associated with several types of human cancers, the mutation analysis of PUS7 was performed in cBioPortal, demonstrating the fusion of PUS7 with SRSF Protein Kinase 2 (SRPK2) in serous ovarian cancer." (PMID 34827123, 2021).
squamous cell carcinoma (1 paper, 2020). A carcinoma arising from squamous epithelial cells. "Subsequently, it was shown that S385 DNp63a phosphorylation is induced by cisplatin in squamous cell carcinoma cells, leading to RNA splicing and ACIN1-mediated cell death via interaction with spliceosome components SAP18, RBM38, ELAVL, SRPK2, SRSF2, and ACIN1." (PMID 33375680, 2020).
tauopathies (1 paper, 2020). "In AD patients, SRPK2 which is important in pre-mRNA splicing is abnormally activated in tauopathies." (PMID 33224974, 2020). "Also, SRPK2, which is abnormally activated in tauopathy in AD, is fragmented by AEP and this proteolytic cleavage is inhibited by AENK as well." (PMID 33224974, 2020).
cancer (17 papers, 2015 to 2026). A tumor composed of atypical neoplastic, often pleomorphic cells that invade other tissues. "Overactive SRPK1 and SRPK2 are associated with more aggressive cancer and increased drug resistance." (PMID 39083441, 2025). "A range of preclinical studies was included, generally addressing four main aspects: cancer-related signalling pathways involving SRPK2; its prognostic associations; its impact on metastatic and/or tumour phenotypes; and the antitumor and/or antimetastatic effects resulting from its inhibition." (PMID 42178601, 2026). "A significant cancer-associated gene SRPK2 was selected for further study." (PMID 35883028, 2022). "Similarly, SRPK2 inhibition and/or dual inhibition of mTOR and O‐linked β‐N‐acetylglucosamine (O‐GlcNAc) in metabolic syndromes or cancer cells dependent on upregulated lipid metabolism has been proposed as a potential anti‐cancer therapy." (PMID 37607329, 2023). "A systematic review was conducted to evaluate the available evidence regarding the tumorigenic and metastatic roles of serine/arginine protein kinase 2 (SRPK2) across different cancer types." (PMID 42178601, 2026). "Subsequently, pre-mACSL3 splicing mediated by BRD4 and SRPK2 ensures the expression abundance of ACSL3 in cancer cells." (PMID 37993451, 2023). "Despite this observation, SRPK1 and SRPK2 seem to act in different ways in cancer, depending on the cell type in which they are expressed." (PMID 36212152, 2022). "Abnormal activity of SRPKs, mostly SRPK1 and SRPK2, has been found in different cancer types, where they act in cellular processes related to tumor development and metastasis, such as angiogenesis, epithelial-mesenchymal transition (EMT), and cell migration." (PMID 36212152, 2022). "Given its role in FASN mRNA and protein expression, we next explored the role of SRPK2 in de novo palmitate synthesis in cancer cells in response to IGF-1 exposure." (PMID 36096767, 2022). "Increases in SRPK1 and SRPK2 were observed in a wide range of distinct cancers, including breast cancer, colorectal cancer, lung cancer, ovarian cancer, hepatocellular carcinoma, pancreatic cancer, leukemia, and gliomas." (PMID 29283381, 2017). "SRPK1 and SRPK2 have also been observed to be overexpressed in various other human cancers, including pancreatic, breast, colon, lung and ovarian." (PMID 26244849, 2015). "SRPK2 may promote cancer development through its canonical role in alternative splicing, as well as through its involvement in diverse cellular signalling pathways." (PMID 42178601, 2026). "Additionally, SRPK2, a related protein, helps cancer cells multiply and progress through the cell cycle by activating a key regulatory protein, E2F1." (PMID 39083441, 2025). "The observation that aberrant nuclear accumulation of SRPK2 has toxic effects on cancer cell proliferation and survival seems also to be overturned by the findings on LAM 621-101 cells that carry inactivating mutations in both alleles of the Tuberous Sclerosis Complex 2 (TSC2) gene (TSC2−/− cells)." (PMID 35719374, 2022). "SRPK2 has been revealed as the effector kinase involved in mammalian target of rapamycin complex 1 (mTORC1)-dependent regulation of lipid metabolism, an important process that supports cancer cell proliferation." (PMID 36212152, 2022). "Therefore, inhibition of SRPK2 or dual inhibition of mTOR and O‐GlcNAc could be promising to suppress the growth of cancer cells dependent on upregulated lipid metabolism." (PMID 37607329, 2023). "Both SRPK2 and FASN are overexpressed in numerous cancers, suggesting potential therapeutic potential." (PMID 36096767, 2022). "Thus, SRPK2, a kinase of the SRPK family, phosphorylates SR proteins and has essential roles in premRNA alternative splicing, which may be linked to human diseases, including cancers, if splicing dysfunctions occur." (PMID 31898732, 2020).
cancer (continued). "Additionally, SRPK2 inhibition had no significant impact on any gene expression in the non-transformed mammary epithelial cell line, MCF-10A, suggesting this a cancer cell specific pathway." (PMID 36096767, 2022).
tumor (16 papers, 2012 to 2026). "As shown, SRPK2 expression was positively associated with tumor differentiation (P = 0.019), as well as the T (P = 0.018), N (P < 0.001) and UICC (P < 0.001) classifications." (PMID 31898732, 2020). "Collectively, these findings highlight SRPK2 as a promising therapeutic target and potential tumour biomarker." (PMID 42178601, 2026). "O-GlcNAc promotes tumor growth by enhancing the intracellular localization of SRPK2 and regulating de novo lipid synthesis in tumor cells at the post-transcriptional level." (PMID 35004688, 2021). "SRPK2 expression was positively associated with clinicopathological characteristics of CRC patients, including tumor differentiation, T stage, N stage and UICC stage." (PMID 31898732, 2020). "It is well known that SRPIN340 has a higher inhibitory activity over SRPK1 compared to SRPK2, implying that this compound would be less effective against tumor cells with higher SRPK2 expression." (PMID 26244849, 2015). "Additionally, this O‐GlcNAc modification enhances the nuclear localization of SRPK2, regulates de novo lipid synthesis in tumor cells at the post‐transcriptional level, and consequently promotes tumor growth." (PMID 40884151, 2025). "Moreover, SRPK2 has been reported to exhibit contradictory functions in different cell contexts promoting either apoptosis or tumor growth." (PMID 35719374, 2022). "SRPK2 is glycosylated to regulate de novo lipid synthesis in tumours." (PMID 35990657, 2022). "Besides, both SRPK1 and SRPK2 mRNA levels were upregulated in tumor tissues comparing with adjacent tissues in our primary cohort." (PMID 33602301, 2021). "Consistent with mRNA data, both SRPK1 and SRPK2 proteins were elevated in tumor tissues." (PMID 33602301, 2021). "Since regulation of SRSF2 involved acetyltransferase Tip60, and kinases SRPK1 and SRPK2, it is conceivable to speculate that in most tumor cells the regulation of SRSF2 was disturbed." (PMID 22957056, 2012). "The effects of inhibition of SRPK1 and SRPK2 by the compounds may be revealed using in vivo tumor models with WT1 mutations rather than cell culture models." (PMID 25581376, 2015). "Several genes splicing events, including KIAA1715/56096/AP, ZNF567/49415/AP, NTMT1/87861/AP, ANAPC15/17570/AD, SRPK2/81284/ES, MTMR11/7413/AP, FNIP2/70999/AP, and TNC/87336/ES, differed significantly between tumor and normal samples." (PMID 31552163, 2019). "SRPIN340 preferentially inhibits SRPK1 and SRPK2, with a higher inhibitory effect on SRPK1, and was shown to reduce human melanoma tumor growth in vivo, but not in vitro, and was attributable to the regulation of VEGF expression and angiogenesis reduction." (PMID 35463320, 2022).
metabolic disorders (3 papers, 2019 to 2025). "mTORC1-S6K1-SRPK2 signaling results in phosphorylation and activation of SR protein, leading to enhanced splicing of lipogenic pre-mRNAs, which suggests SRPK2 as a target for metabolic disorders induced by mTORC1." (PMID 35879299, 2022). "mTORC1, a potential therapeutic target for metabolic disorders, promotes lipid biogenesis by activating the SRPK2 gene, a regulator of RNA-binding SR protein." (PMID 31796646, 2019).
adenocarcinoma (1 paper, 2012). A common cancer characterized by the presence of malignant glandular cells. "In this study, we investigated the status of SRSF1, SRSF2 and its phosphorylated form P-SRSF2, as well as of SRPK1 and SRPK2 in a series of 107 NSCLC, including 54 adenocarcinoma (ADC) and 53 squamous cell carcinoma (SCC)." (PMID 23071587, 2012).
neurodevelopmental disorder (1 paper, 2024). A behavioral and cognitive disorder with onset during the developmental period that involves impaired or aberrant development of intellectual, motor, or social functions. "Interestingly, we observed enrichment of SRPK2-regulated phospho-sites upon dTAG-PPP2CA degradation, and even some phospho-sites on SRPK2 itself, potentially offering some insight into the association of hyper-phosphorylated hits with neurodevelopmental disorders." (PMID 38450154, 2024).
SRPK2 also shares sentences with these, for which no sentence is quoted: colon cancer (2 papers); neurodegenerative disease (2); viral infection (2); acute myeloid leukemia (1); Anxiety (1); autism (1); autism spectrum disorder (1); Ebstein anomaly (1); glioma (1); infection (1); lung carcinoma (1); neuroblastoma (1); Parkinsonism (1); schizophrenia (1); skin cutaneous melanoma (1); triple-negative breast carcinoma (1).